FABP5 (fatty acid binding protein 5)
Diseases named in the same sentence as FABP5 in open-access papers (continued):
Sharing a sentence is not in itself a finding about the gene and the disease.
tumor (continued). "For example, the observed reduced expression of Fabp5 downstream of Nfkb, one of the genes defining the profile of resting tumor-associated macrophages, might be an indication of a tumor microenvironment that supports rather than inhibits tumor growth in mice exposed to cigarette smoke." (PMID 26109882, 2014). "Similar to FABP4, FABP5 expression did not correlate with patient age, BMI and tumor size." (PMID 40106183, 2025). "Furthermore, FABP5 regulates the expression of VEGF through PPARγ and enhances the expression of other angiogenic factors, including EGF and IL‐6, thereby promoting tumor angiogenesis." (PMID 40178066, 2025). "This suggests that the correlation between FABP5 expression and tumor differentiation may not be evident in studies conducted in China." (PMID 40178066, 2025). "Additionally, FABP5 contributes to immune evasion by positively regulating the programmed cell death ligand 1 (PD-L1), the tumour necrosis factor (TNF), and IL-17 expression, and reshaping the tumour immune microenvironment and facilitating immune escape." (PMID 41149452, 2025). "Therefore, stromal FABP5 expression could be explored as potential predictive biomarker and furthermore, the ratio of FABP5:CRABP2 may have a correlation with tumor progression and overall survival." (PMID 41584580, 2025). "We also measured expressions of FABP5, GPNMB and OLR1 in the tumors and adjacent tissues, and found that they were expressed at significantly higher levels in the tumors than in the adjacent normal tissues, again confirming the ability of spheroids to mimic the in vivo tumor." (PMID 40176808, 2025). "Given that FABP5 is expressed in both HCC cells and TAMs and is involved in processing the abundant lipid molecules in the TME, it may play a key role in the metabolic communication between tumor and immune cells." (PMID 41035647, 2025). "Multiple studies have shown that FABP5 is significantly overexpressed in HCC tissues compared to adjacent non-tumourous liver and correlates with aggressive clinical features, such as poor differentiation, microvascular invasion, larger tumour size, and reduced overall and disease-free survival." (PMID 41149452, 2025). "Moreover, the FABP5 mRNA level was lower, but not to a significant extent, in tumor than control tissues." (PMID 37416772, 2023). "Notably, surface FABP5 expression increased on CD8+ T cells in the peritoneal cavity and omentum during the first week of tumor progression, compared with their counterparts in naïve mice, but markedly declined thereafter as ascites and omental metastatic lesions developed." (PMID 38168227, 2023). "Furthermore, FABP5 promotes tumour cell growth in numerous cell types and is a negative prognostic marker in renal cell carcinoma." (PMID 34099718, 2021). "The mRNA and protein expression of FABP5 was significantly higher in tumours from mice treated with bevacizumab than in mice treated with the control.Moreover, we examined the expression of CA9 (a hypoxia marker) and FABP5 in tumour sections taken from xenograft mouse tumours by IHC." (PMID 32550890, 2020). "Moreover, FABP5 overexpression was significantly correlated with LNM (P = 0.001), body mass index (BMI) (P = 0.013), FIGO stage (P < 0.001), lymphovascular space invasion (LVSI) (P = 0.004), and tumour size (P = 0.02)." (PMID 32550890, 2020). "As HIF-1α induces the expression of genes related with tumor survival, we assessed the mRNA levels of CCND2, VEGF, BNIP3L, and CA9, and found that CCND2, VEGF, BNIP3L, and CA9 were upregulated when spheroids were treated with OA, whereas their mRNA levels decreased upon FABP5 or HIF-1α silencing." (PMID 33128030, 2020). "However, it should be noted that inhibiting FABP5 expression and lipid uptake does not have an impact on killing tumor cells, which suggests that the different biological features of Tex depend on distinct metabolic mechanisms." (PMID 32611686, 2020).
tumor (continued). "Thus targeting instead the FABP5- PPARγ-VEGF axis, which we suggest, gradually replaces the AR-mediated signalling pathway in tumour progression, could be an alternative way for treatment of CRPC." (PMID 31258834, 2019). "Similarly, Wang and colleagues described a novel mechanism in which FFAs were released by adipocytes after lipolysis induced by tumor secretions and were transferred into tumor cells to enhance FFA β-oxidation, in which FFA transformation maybe attributed to FABP5 high expression." (PMID 31500658, 2019). "ND GBM pre-surgery saliva (NDT0) showed the exclusive characterization of peptide fragments of CDA, HOPX, FABP5, WIPF3, VOPP1, AHNAK, and DAZAP1 proteins, which, to the best of our knowledge, have not been previously identified in relation to GBM tumor." (PMID 41155285, 2025). "We showed a role for FABP5 modulation of MMP9 secretion, and not MMP2, in TNBC cells, which plays an important role in degrading the extracellular matrix and the invasion of tumor cells." (PMID 25779666, 2015). "However, mRNA expression levels of FABP1, FABP2, FABP5, FABP6, FABP7, FABP9, or FABP12 did not significantly differ in different tumor stages in CRC patients." (PMID 34680577, 2021). "In summary, the IHC data from tumors and lungs suggest that the expression of FABP4, FABP5, or CYP2C19 is not solely come from cancer cells but also from resident or infiltrating stromal cells in tumor and lung microenvironments, affecting TNBC tumor growth or metastasis." (PMID 31941087, 2020).
cancer (126 papers, 2008 to 2026). A tumor composed of atypical neoplastic, often pleomorphic cells that invade other tissues. "FABP5 expression is also closely associated with regulating programmed cell death, including apoptosis and autophagy in cancer." (PMID 39871325, 2025). "High FABP5 expression is associated with poor prognosis in various cancers, indicating its potential as a biomarker for early diagnosis and prognostic assessment." (PMID 40717587, 2025). "Fatty-acid-binding protein 5 (FABP5), which shuttles ligands from the cytosol to PPARβ/δ, underlines the importance of endogenous PPARβ/δ ligands for cancer growth, as knockout of FABP5 was sufficient to reduce mammary tumorigenesis." (PMID 35954274, 2022). "The mechanisms underlying the specific up-regulation of the FABP5 in these cancers remained poorly characterized." (PMID 32579175, 2020). "FABP5 has also been identified as a tumor-associated antigen, which is highly expressed in various cancers." (PMID 19602232, 2009). "FABP5 is overexpressed in several types of cancer and associated with poor prognosis." (PMID 33128030, 2020). "FABP5 is a well-characterized protein involved in several types of cancer, as it promotes cell proliferation, migration, and invasion; thus, its expression has been associated with poor cancer prognosis." (PMID 33128030, 2020). "A patent entitled “Biomarker compositions and methods (WO 2014082083 A1)” describes a technique to detect cancer-associated EVs in bodily fluids by staining lipid layers of EVs, and various cancer-associated antigens including FABP5 were described as potential microvesicle-associated antigens." (PMID 28211531, 2017). "It would be interesting to assess whether the regulatory mechanisms underlying the upregulation of FABP5 gene expression and the functions of FABP5 protein in cancer cells are mediated by a common signaling pathway." (PMID 27047747, 2016). "Conversely, the RA signal mediated by the FABP5/PPAR pathway may promote cancer cell survival by activating some cancer-associated genes." (PMID 25797252, 2015). "Therefore, FABP5 might be implicated in cancer metastasis through the reprogramming of lipid metabolism." (PMID 35445019, 2022). "Recent studies have indicated that FABP5 plays important roles in the regulation of gene expression associated with cell growth and differentiation since FAs are required as an energy source and for production of cellular signalling molecules and the formation of membrane components during cancer." (PMID 33837625, 2021). "However, the molecular mechanisms underlying the connection between high expression of FABP5 and cancer cell proliferation remains unclear." (PMID 30167092, 2018). "FABP5 is abnormally overexpressed in various cancers, driving metabolic reprogramming, immune suppression, and metastasis through the activation of pro-tumorigenic transcription factors, and is significantly associated with poor prognosis." (PMID 40717587, 2025). "A glutathione-derived chemical tool was developed to mimic glutathionylation in proteins, demonstrating that the glutathione modification of FABP5 cysteine 127 induces cancer cell migration." (PMID 40487857, 2025). "Recent study has found that FABP5 plays a role in metabolic diseases and is crucial in the progression of various cancers, promoting cell proliferation, migration, and invasion." (PMID 39871325, 2025). "The increased levels of FABP5 in PCa significantly correlate with the degree of malignancy measured by Gleason scores, with the highest level of FABP5 expressed in advanced and highly malignant carcinomas." (PMID 41009695, 2025). "FABP5 is reported to be highly expressed in a variety of cancers and regulates the development and progression of cancer cells including HCC through its participation in the EMT signaling pathway." (PMID 39194582, 2024). "In the current study, we have uncovered the upregulated ALKBH5 activated FABP5 to promote the lipid metabolism of cancer." (PMID 37858219, 2023).
cancer (continued). "In this study, we found that T-C6 highly expressed KRT13 and FABP5 and clustered in the center of the cancer nest." (PMID 37124494, 2023). "In this study, we made a pan-cancer analysis of FABP5 based on the clinical data from The Cancer Genome Atlas database for the first time." (PMID 36906605, 2023). "Conversely, cancer cell survival is enhanced when a low ratio of CRABP-II/FABP5 expression profiles exist." (PMID 37689790, 2023). "An adjusted (Tukey) box-plot analyses showed evidence of lower concentrations of SPRR1B, CRNN, TXN and FABP5 in cancers compared to controls." (PMID 36807337, 2023). "Studies have found that the high expression of FABP5 in cancer cells promotes lipolysis, and the lipolysis of adipocytes in FABP5 transgenic mice is increased." (PMID 37430185, 2023). "Taken together, our cross-species cancer genomics analysis points to FABP5 as the PC relevant candidate driver of the gene family." (PMID 38201488, 2023). "In cancer cells with a high ratio of CRABP-II/FABP5 expression, ATRA functions in a proapoptotic manner, eliciting anti-neoplastic activity." (PMID 37689790, 2023). "Several studies have found that FABP5 was involved in the process of several cancers through metabolic reprogramming." (PMID 37430185, 2023). "Multiple studies have shown that peroxisome proliferator-activated receptors (PPARs, including PPARα, PPARβ and PPARγ), markers of lipid metabolism-related signalling pathways, are activated by FABP5 and are involved in the progression of human cancers." (PMID 36168624, 2022). "Taking FC and binding score, KEGG pathway analysis and association with human cancers into account as screening standards 26, only the PPAR signaling pathway was related to BCa, and thus, only FABP5 was selected for further verification." (PMID 36168624, 2022). "Mechanism studies have revealed that FABP5 regulates tumorigenesis and cancer progression by regulating different pathways including MMP-2/MMP-9, PI3K/AKT, and PPARs pathways." (PMID 35445019, 2022). "Silencing or down-regulating FABP5 in human cancer cells inhibits cell proliferation and decreases the expression of the genes which are involved in altered lipid metabolism, lipolysis, and de novo synthesis of fatty acids in various tumors." (PMID 35445019, 2022). "VEGF has been identified as a key mediator of angiogenesis in cancer and FABP5 has been positively correlated with VEGF expression." (PMID 35445019, 2022). "Upregulated lncDBET activates the PPAR signalling pathway to promote the lipid metabolism of cancer cells through direct interaction with FABP5, thus promoting the malignant progression of BCa." (PMID 36168624, 2022). "High FABP5 expression enhances fatty acid transport to cancer cells used as a new energy source to meet the needs of rapid cell growth." (PMID 35459093, 2022). "FABP5/PPARβ/δ pathway is critical in tumorigenesis and cancer growth, which is similar to its role in enhancing the proliferation of keratinocytes." (PMID 35445019, 2022). "FABP5 was also highly expressed in invasive cancer cell lines (LI-7 and HLE) than in the noninvasive cell lines (Hep3B and HepG2) of HCC." (PMID 35445019, 2022). "Upregulated lncDBET activated the PPAR signalling pathway to promote the lipid metabolism of cancer cells through direct interaction with FABP5, thus promoting the malignant progression of BCa in vitro and in vivo." (PMID 36168624, 2022). "Collectively, FABP5 is upregulated in various cancers, which promotes cancers progression or metastasis by reprogramming fatty acid metabolism through the NF-κB signaling pathway or enhancing HIF-1α activity." (PMID 34934042, 2021). "Further research is required to fully establish the contribution of each specific gene, including four outstanding genes (Slc41a3, Fabp5, Mthfd1l and Igdcc4) with clinical relevance in human cancer." (PMID 33917315, 2021).
cancer (continued). "For the cancer specimens, FABP5 high expression was observed in 58.7% (101/172) and the difference was statistically significant." (PMID 34632074, 2021). "A recent report revealed the contribution of FABP5 to the reprogramming of lipid metabolism in cancer." (PMID 33128030, 2020). "Our findings also provided new insights into the role of OA/FABP5/HIF-1α axis in the lipid-metabolism reprogramming involved in cancer cell growth in HCC." (PMID 33128030, 2020). "Of these five FABPs, FABP4 and FABP5 have been the most intensively studied in terms of progression of various cancers, including PCa." (PMID 33352874, 2020). "Several independent studies have shown that FABP5 is involved in the development and progression of various cancers 16-24." (PMID 32550890, 2020). "The results also suggest that the FABP5/HIF-1α axis can be used to modulate lipid metabolism in cancer cells." (PMID 33128030, 2020). "This formed the foundation of our approach to search for compounds with potential anti-cancer activities in grape stem extracts by assessing inhibitory activity on FABP5 gene expression." (PMID 31427660, 2019). "We previously showed that high expression of the FABP5 gene plays an important role in cell proliferation and metastasis in various cancer cells." (PMID 31427660, 2019). "Knockdown of FABP5 significantly weakened the migration ability of co-cultivated cancer cells, implicating a critical impact from the surrounding adipocytes." (PMID 29914512, 2018). "In the present study, FABP5 was scarcely expressed in the normal breast epithelial cell line MCF10A but was highly expressed in cancer cell lines." (PMID 29914512, 2018). "We first examined FABP5 mRNA expression in various PCa cell lines and found that FABP5 was strongly expressed in DU-145, PC-3 and PC-3M (malignant cancer cell lines)." (PMID 30167092, 2018). "Here we examined and revealed the mechanisms of FABP5 in cancer cell proliferation and metabolism in PCa via a PPARβ/δ-independent pathway." (PMID 30167092, 2018). "Epidermal or cutaneous fatty acid-binding protein is an intracellular lipid-binding protein, also known as FABP5, and its expression level is closely related to cancer cell proliferation and metastatic activities in various types of carcinoma." (PMID 30167092, 2018). "FABP5 is also increased in various cancers, including triple negative breast cancer, bladder cancer, pancreatic cancer, oral squamous cell carcinoma, and intrahepatic cholangiocarcinoma." (PMID 30167092, 2018). "These compounds also suppressed the expression of cancer-promoting genes such as FABP5 and invasion of cancer cells, suggesting that they represent promising anti-metastatic agents." (PMID 28798415, 2017). "FABP5 Upregulation has been related to promoted cancer cell proliferation and metastasis, therefore FABP5 also known as oncogenic FABP." (PMID 29237483, 2017). "Further studies on the mechanisms regulating FABP5 gene expression in cancer cells are now in progress in our laboratory." (PMID 27047747, 2016). "FABP5 transports RA to the nucleus and delivers it to PPARβ/δ, activating non-genomic pathways, leading to proliferative and antiapoptotic effects on cancer cells." (PMID 27070597, 2016). "Changes in FABP expression have been associated with various diseases including several forms of cancer with FABP5 being the most well characterized FABP isoform in cancer cell biology." (PMID 25866768, 2015). "For example, prostate, endometrial, liver, pancreatic, and breast cancers have increased FABP5 gene or protein expression." (PMID 25866768, 2015). "It has been well established that FABP5 suppresses sensitivity of cancer cells to retinoic acid, and the fact that there is low expression level of FABP5 in SkBr3 suggests sensitivity of these cells to retinoic acid." (PMID 25260874, 2014).